TBC1D3E (TBC1 domain family member 3E)
Description:
Acts as a GTPase activating protein for RAB5. Does not act on RAB4 or RAB11 (By similarity).
Synonyms: PRC17
Gene: Protein-coding gene on chromosome 17 (38,127,951 to 38,138,868, forward strand). Ensembl gene ENSG00000278599.
Subcellular location: Cell membrane
Subcellular location (Human Protein Atlas): Vesicles
Gene Ontology:
Molecular function: GTPase activator activity
Cellular component: plasma membrane; endosome; membrane
Homologues: Orthologues: chimpanzee TBC1D3B (96% identical). Paralogues in human: TBC1D3 (99% identical), TBC1D3C (99% identical), TBC1D3K (99% identical), TBC1D3D (99% identical), TBC1D3F (99% identical), TBC1D3I (99% identical), TBC1D3H (99% identical), TBC1D3L (99% identical), TBC1D3G (99% identical), TBC1D3B (99% identical), TBC1D26 (30% identical), USP6NL (29% identical), and 33 more.
Diseases named in the same sentence as TBC1D3E in open-access papers:
TBC1D3E is named in the same sentence as 2 diseases in open-access papers, as found by Europe PMC text mining. Sharing a sentence is not in itself a finding about the gene and the disease.
TBC1D3E shares sentences with these, for which no sentence is quoted: cancer (1 paper); tumor (1).